MTOR (mechanistic target of rapamycin kinase)
Diseases named in the same sentence as MTOR in open-access papers (continued):
Sharing a sentence is not in itself a finding about the gene and the disease.
tumor (continued). "The AKT/mTOR signaling pathway is involved in tumor metastasis and is closely associated with autophagy." (PMID 37138336, 2023). "For example, activation of the PI3K/Akt/mTOR pathway is a major cause of BC resistance to anti-tumor therapies." (PMID 37218922, 2023). "Peripheral localization of lysosomes promotes LE leading to remodeling of the extracellular matrix and supporting migration and invasion and increases lysosome association with mammalian target of rapamycin (mTOR) supporting tumor growth." (PMID 37003503, 2023). "On the other hand, the over-activation of PI3K/AKT/mTOR signaling pathways in tumor cells is associated with metabolic rewiring and immune evasion mechanisms." (PMID 38435444, 2023). "WNT and mTOR are components of signaling pathways within tumor cells, and dysfunction of either protein is associated with the pathogenesis of neoplasms." (PMID 37176048, 2023). "The analysis revealed that the pathways enrichment of the MAPK, WNT, Notch, NOD-like receptor, RIG I-like receptor and mTOR signalling pathways, which are extensively involved in tumour evolution, in the high-risk subgroup." (PMID 37857017, 2023). "On the other hand, the abnormal activation of mTOR, a hub for the regulation of intracellular energy metabolism, can cause enhanced metabolism, like protein synthesis and aerobic glycolysis, in tumor cells." (PMID 38276291, 2023). "Is the increased CTL and NK cell function associated with an increase in mTOR activity in the tumor microenvironment?" (PMID 36614196, 2023). "FBXW7 mutation in CRC leads to tumor cell proliferation, increases resistance to paclitaxel, 5-fluorouracil and oxaliplatin, as well as becomes sensitive to mTOR inhibitors." (PMID 37404825, 2023). "Our previous studies demonstrated that ONC206 caused apoptosis and inhibited tumor growth in a transgenic mouse model of EC through inhibition of the AKT/mTOR pathway." (PMID 37069726, 2023). "The PI3K/Akt/mTOR pathway has been associated with the development and progression of different neoplastic diseases." (PMID 36765661, 2023). "The EGFR/AREG axis activation, coupled with the mutational patterns in PI3K/AKT/mTOR and cell cycle pathways warrants caution in considering MECs as low‐risk neoplasms." (PMID 36916425, 2023). "The phosphatidylinositol 3-kinase (PI3K)/protein kinase B (AKT)/mammalian target of rapamycin (mTOR) pathway mutations are frequent in BC (20–40%) and are significant causes of aggressive tumor behavior, as well as treatment resistance." (PMID 36672617, 2023). "According to previous findings, different risk groups differed significantly in proliferative capacity and activity of the PI3K/AKT/mTOR signal pathway, which is widely implicated in mitochondrial metabolism and tumor drug resistance." (PMID 36909185, 2023). "This genomic profiling is conducted using tumor tissues or liquid biopsies to detect mutations, deletions, or amplifications in genes related to the mTOR pathway, such as PTEN, PI3K, AKT, and other key components." (PMID 37834408, 2023). "In PDAC, activation of the oncogenic PI3K/AKT/mTOR signalling is linked to increased tumour growth, drug resistance and epithelial‐mesenchymal transition, weakened apoptosis and tumour immunogenicity, and worse pathological and clinical outcomes." (PMID 38037549, 2023). "The restriction of tumor growth is associated with the down-regulation of mTOR and Hedgehog (Hh) signaling, both of which are implicated in the pathogenesis of RMS." (PMID 37958442, 2023). "We discovered that the levels of WNT-1 and mTOR expression in the cellular compartments were associated with tumor grade and staging." (PMID 37176048, 2023). "A mutation in a member of the PI3K/AKT/mTOR signalling pathway was present in 19% (4/21) of H3-K27M-FGFR1MUT tumours." (PMID 38066305, 2023). "Recent studies have demonstrated that tumor radioresistance is linked to aberrant activation of the PI3K/AKT/mTOR pathway and glycolysis." (PMID 37551838, 2023).
tumor (continued). "In particular, we explored the role of VHL, mTOR, chromatin modulators, DNA repair genes, cyclin-dependent kinases, and tumor mutation burden." (PMID 37887570, 2023). "In glioblastoma cells, removing lipids from the plasma membrane reduced Akt-1 action, which inhibited its downstream target mTOR, causing death and decreased tumor growth." (PMID 37710280, 2023). "Nevertheless, rather than exclusively targeting mTORC1 component of mTOR pathway, expression analysis profiling of patient-derived TNBC tumours in conjunction with in vivo studies on TNBC mice revealed a higher susceptibility of TNBC to mTOR targeting." (PMID 36290817, 2022). "We also analyzed the correlation between MTOR and tumor mutational burden (TMB), the tumor immune microenvironment, and microsatellite instability (MSI) status." (PMID 35883111, 2022). "This has been reversed with LY 294002, a PI3K inhibitor, or rapamycin, an mTOR inhibitor, in vitro and in vivo murine models; the latter was also associated with decreased tumor growth." (PMID 35806208, 2022). "One study analyzed publicly available tumor genome sequence data from more than 400 samples, and identified 33 mutations in MTOR related to hyperactivation, which can strongly activate the downstream effectors (4EBP1 and S6K1) to promote the tumorigenesis." (PMID 35326708, 2022). "Four children with DIPG for whom ACVR1 mutations were confirmed in stereotactic tumor biopsy specimens and/or peripheral blood were treated with vandetanib and an mTOR inhibitor." (PMID 34551970, 2022). "This tumor-promoting effect was associated with Akt and mTOR activation, and tumor cell proliferation, and extravasation." (PMID 35565382, 2022). "In the neoplastic development and progression, activated RTKs cause activation of the downstream signaling PI3K/Akt/mTOR cascade, contributing to tumor progression, apoptosis resistance, and metastasis." (PMID 39282148, 2022). "In general, investigations have shown that mTOR signaling activation is associated with enhanced tumor progression, survival, and invasion, as well as frequently reduced survivability of the affected patient." (PMID 36428613, 2022). "In previous work, we have described small inhibitors that bind to the PDZ domain of DEPTOR, prevent DEPTOR/mTOR association in MM cells, induce acute activation of mTOR, and MM tumor cell apoptosis." (PMID 35216969, 2022). "Activation of the PI3K/Akt/mTOR signaling axis has been implicated in therapeutic resistance and metabolic reprogramming of many tumor types in response to both chemotherapy and targeted therapies." (PMID 36077374, 2022). "Increased mTOR signaling is particularly related to human malignancies defined by the loss or mutation of critical tumor suppressors including STK11, TSC1/2, and PTEN which seem to be important for regulating the PI3K/Akt pathway." (PMID 36109789, 2022). "mTOR is part of the phosphatidylinositol 3-kinase/Akt/mTOR signaling pathway, which is implicated in tumor angiogenesis." (PMID 36212393, 2022). "Many PI3K/AKT/mTOR inhibitors have been investigated in clinical trials for the treatment of PTEN-deficient tumours with mixed results depending on the molecular background." (PMID 35326717, 2022). "Instead, tumor stratification was qualitatively associated with the interaction of several genomic features (mtDNA mutations, mTOR pathway activation, and LOH from uniparental disomy) and pathology subtypes (HWIDE/HMIN status)." (PMID 35731870, 2022). "Multiple tumor driver genes that are associated with spermatogenesis pathway such as mTOR, EZH2, NF2, DCC and MLF1 had high enrichment score in the EGFR group." (PMID 35428753, 2022). "The association of RIOK2 with bystin-like protein and mechanistic target of rapamycin kinase promotes tumor cell growth and survival through activation of AKT signaling in gliomas." (PMID 36518977, 2022).
tumor (continued). "The PI3K/Akt/mTOR signalling pathway has been confirmed to be implicated in the development of many tumor diseases as the main downstream transduction pathway of PTEN." (PMID 36245984, 2022). "Phosphatidylinositol 3-kinase (PI3K)/protein kinase B (AKT)/mammalian target of rapamycin (mTOR) pathway is an important survival pathway in tumor cells, associated with its aggressive growth and malignant progression." (PMID 35574327, 2022). "The activation of the PI3K/AKT/mTOR signalling pathway or loss of PTEN tumour suppression is common in TNBC, making this pathway an attractive target for therapy." (PMID 35877237, 2022). "Thedrug temsirolimus, which has effects of disrupting the mTOR pathwayand triggering apoptosis in tumor cells, causes THP-1 cells to expressASC and to be involved in apoptosis." (PMID 35601322, 2022). "Wang and colleagues demonstrated the anti-migratory and apoptotic activity of 4 in A549 cells, associated with the inhibition of the Pi3K/AKT/mTOR signalling pathway and activation of the tumor-suppressor, E-cadherin." (PMID 35209235, 2022). "Intriguingly, the phosphoinositide 3-kinase/mTOR (PI3K/mTOR) signaling pathway–related gene expression profile was altered in tumor-infiltrating SENP7-deficient CD8+ T cells." (PMID 35143421, 2022). "As we know, TLR4 recognizes cathepsin K to activate the M2 polarization of tumor-associated macrophages (TAMs) through an mTOR-dependent pathway, resulting in tumor metastasis." (PMID 36204682, 2022). "Mutation of PBRM1 (p = 0.0003) and mutation of mTOR (p = 0.005) were also associated with increased HIF metagene scores in this tumor type, consistent with previous findings." (PMID 36384128, 2022). "Antitumor effects of mTOR inhibitors are linked to tumor development, angiogenesis, and invasion inhibition." (PMID 36293326, 2022). "Meanwhile, an ROS scavenger attenuated the hyperactivation of the mTOR pathway in Tsc1 insufficient and Kras-mutated tumor cells." (PMID 36451866, 2022). "Tuberous sclerosis complex 1 (TSC1) is a tumor suppressor that promotes the inhibition of mechanistic target of rapamycin (mTOR) pathway, and mutations in TSC1 lead to a rare complex disorder of the same name." (PMID 35645731, 2022). "Overactivation of the Akt/mTOR pathway is closely associated with tumorigenesis, tumor progression, and drug resistance." (PMID 36568517, 2022). "The upregulation of mTOR is associated with lower tumor differentiation, worse prognosis, and early recurrence." (PMID 36187118, 2022). "We first determined how blockage of ATM‐associated DNA damage affects MAPK, and mTOR signaling pathways during citrate‐mediated tumor cell senescence." (PMID 34747157, 2022). "The tumor size and regional lymph node affections were associated with a decrease in the mTOR mRNA level." (PMID 35877414, 2022). "In this review, we examine the emerging association of mTOR signaling components with certain protein tools of tumor mechanobiology." (PMID 35163745, 2022). "We next explored the potential causative relationships and interactions among ATM‐associated DNA damage, MAPK and mTOR signaling pathways in the process of tumor cell senescence mediated by citrate." (PMID 34747157, 2022). "These inhibitors inhibit the activation of PI3K, AKT, and mTOR by inhibiting these three targets, which in turn is closely linked to the degree of tumor metastasis and related disease progression." (PMID 35694243, 2022). "On the other hand, a loss of PTEN, a negative regulator of the PI3K/AKT/mTOR pathway, is present in approximately 60% of mCRPC patients which is related to worse prognosis, treatment resistance, tumor grade, tumor stage, and risk of recurrence." (PMID 35053602, 2022). "Overactivation of phosphatidylinositol 3-kinase/protein kinase B/mammalian target of rapamycin (PI3K/AKT/mTOR) signaling is associated with tumor-acquired chemotherapy resistance." (PMID 35078498, 2022).
tumor (continued). "STK11 inhibits the mammalian target of rapamycin (mTOR) pathway, and its mutations are linked to various tumor types in both syndromic and sporadic contexts." (PMID 35910641, 2022). "Frequent mutations and loss of function in PTEN tumor suppressor gene leads to constitutive activation of Akt protein hence activation of PI3K/Akt/mTOR cell survival pathway." (PMID 35331184, 2022). "A similar study demonstrated that AKT/mTOR-mediated suppression of autophagy-mediated apoptosis by long noncoding RNA CASC9 is associated with tumor progression in OSCCs." (PMID 35723362, 2022). "In prostate cancer, exercise induced the upregulation of HIF-1α and VEGF via activating MEK/MAPK and PI3K/mTOR signaling pathway, which is associated with a shift to tumor vascular normalization and inhibition of tumor metastasis." (PMID 36313283, 2022). "Under adverse conditions such as cell hypoxia and nutrient deficiency, the PI3K/AKT/mTOR pathway is inhibited, which can induce the occurrence of autophagy, to maintain tumor cell survival." (PMID 36544104, 2022). "Tumor necrosis releases potassium ions interfere with mTOR signaling causing impaired function and T-cells overexpressing potassium channel can reverse the tumor resistance." (PMID 36569859, 2022). "Our findings indicate the prognostic value of MTOR in CRC and demonstrate the potential associations between MTOR and tumor mutation." (PMID 35883111, 2022). "mTOR signal is one of the key genetic variation targets in cancers, which is often associated with tumor occurrence and progression." (PMID 35574327, 2022). "Since PI3K/AKT triggers downstream signals to mTOR for cellular proliferation, miR-126 loss increases tumor formation." (PMID 36483029, 2022). "A tissue microarray‐based study, in which 200 HCCs were analyzed, reported that the overexpression of p‐AKT and p‐mTOR was associated with the tumor grade, as well as intrahepatic metastasis, vascular invasion, the TNM stage, and a high Ki‐67 labeling index." (PMID 35174643, 2022). "The AMPK signalling pathway is associated with cellular energy homeostasis, and the mTOR signalling pathway is closely associated with tumourigenesis, especially with the changes in tumour metabolism." (PMID 35735113, 2022). "VHL loss of function also causes the hyperactivation of mTOR, which correlates with tumor progression and poor outcomes in ccRCC patients." (PMID 35892875, 2022). "Within the Akt/mTOR pathway, mutations have been demonstrated in patient-derived tumours within PIK3CA, PTEN, and AKT1 that lead to increased Akt phosphorylation, mTOR-mediated survival signalling, and early disease progression." (PMID 34069119, 2021). "Some mechanisms that limit the efficacy of rapalogs have been identified and include activation of alternate proliferative signaling pathways, treatment resistance mutations of mTOR and more problematic tumor heterogeneity." (PMID 33802831, 2021). "Tumor cells with an activating AKT1 mutation can be targeted by AKT1 inhibitors or agents blocking mTOR, a downstream member of the AKT1 signaling pathway." (PMID 34885114, 2021). "It has been reported that abnormal activation of mTOR can cause cell cycle activation, thereby promoting tumor formation and tumor cell invasion, metastasis and formation of blood vessels." (PMID 34765011, 2021). "Actually, TSC2 encodes a tumor suppressor, which is capable of stimulating specific GTPases and negatively regulate mTOR signaling." (PMID 34249677, 2021). "In some tumors like PCa, upregulation and the interplay between MYC, AR, and the mTOR mutations cause Gln addiction when Gln becomes a conditional EAA for tumor growth and survival." (PMID 33401748, 2021). "Recent data also supported the role of FNDC5/irisin in alleviating oxidative stress caused by doxorubicin-induced cardiac toxicity in an AKT/mTOR-dependent pathway, with improved the sensitivity of the tumor response to chemotherapy." (PMID 34899376, 2021).
tumor (continued). "More importantly, a genetic approach to exploring the association between mTOR signaling and the anti-tumor effects of puerarin needs to be implemented." (PMID 34863080, 2021). "Hyperactivation of the PI3K/AKT/mTOR pathway is associated with increased tumor survival, drug resistance, and poor clinical outcome." (PMID 33668685, 2021). "-Hypersegmentation and induction of cytotoxic activity of tumor-associated neutrophils, mediated by mTOR." (PMID 34094953, 2021). "The PI3K/Akt/mTOR signaling pathway has been also implicated in tumor cell proliferation, metastasis and apoptosis." (PMID 34895234, 2021). "For example, tumor cells with a mesenchymal subtype were susceptible to PI3K/AKT/mTOR inhibitors, including ZSTK474 and GSK690693." (PMID 34926441, 2021). "Recent evidence demonstrates that the activation of the PI3K/Akt/mTOR pathway is also implicated in the pathogenesis of NB, and is correlated with tumor progression and a poor prognosis." (PMID 34199959, 2021). "PI3K/AKT/mTOR signaling is critical in controlling immune cell function and has been linked to immunosuppressive immune cell function in the tumor milieu." (PMID 33807608, 2021). "Loss of TSC activity results in continuous activation of the mTOR pathway, which is also characteristic to various neoplasms where upstream mutations or signalling malfunction both result in mTOR activation." (PMID 34178631, 2021). "As the core regulator of metabolic and translational reprogramming, mTOR is mainly involved in the central tumor immune microenvironment, affecting tumor-associated immune cells to undergo phenotypic and functional reprogramming in TME." (PMID 35250965, 2021). "It was stated that mTOR is implicated in leukemic cell growth, tumor-associated angiogenesis, and VEGF expression in AML." (PMID 33828590, 2021). "Even in the absence of mutations in PIK3CA and Akt1, the expression of PI3K/AKT/mTOR pathway components is also expressed in EC and is associated with tumor grade, tumor stage, and clinicopathologic feature." (PMID 34046062, 2021). "It was also shown that suppression of the mTOR inhibitor DEPTOR in VHL-deficient ccRCC accelerated tumor cell proliferation." (PMID 34290272, 2021). "The mechanism underlying mitochondrial fission and fragmentation in tumor infiltrating NK cells is activation of an mTOR-Drp1 axis due to the hypoxic tumor microenvironment." (PMID 34199142, 2021). "In turn, mTOR-mediated glycolysis is associated with the promoted suppressive function of tumor-infiltrating M-MDSCs." (PMID 35250965, 2021). "Due to this impaired regulation, the mTOR signaling pathway remained continuously active, leading to the uncontrolled proliferation of mutated cells and, as a consequence, to tumor formation." (PMID 33821877, 2021). "Sestrin 2 associated with AMPK to inhibit mTOR signaling and enhanced radiation therapy-induced tumor cell death." (PMID 34784907, 2021). "The first is that activation of mTOR regulates the upstream of autophagy to cause tumor more sensitive, while TFEB regulates the downstream lysosomal fusion to promote tumor progression." (PMID 34830772, 2021). "In 27 patients, the tumor harbored gene variants which were previously reported to be indicative for mTOR activation." (PMID 33935721, 2021). "Third, hyperactivation of the mTOR pathway can arise from mutations in upstream elements including, tumor suppressors and oncogenes, which in physiological conditions render it activation or suppression, respectively." (PMID 35250965, 2021). "According to this literature review, the mechanisms used by sestrin 2 to inhibit tumor growth are mainly associated with mTOR, iNOS, XIAP, and HIF-1α signaling pathways." (PMID 34784907, 2021). "LPA can mediate increases in tumor-associated macrophages through the AKT/mTOR pathway, which in turn leads to tumor promotion." (PMID 34440828, 2021).